RPL17P3 (ribosomal protein L17 pseudogene 3)
Gene: Unprocessed pseudogene on chromosome 14 (81,001,166 to 81,001,786, reverse strand). Ensembl gene ENSG00000271705.
Diseases named in the same sentence as RPL17P3 in open-access papers:
RPL17P3 is named in the same sentence as 1 disease in open-access papers, as found by Europe PMC text mining. Sharing a sentence is not in itself a finding about the gene and the disease.
RPL17P3 shares sentences with these, for which no sentence is quoted: hyperthyroidism (1 paper).